PVT1 (Pvt1 oncogene)
Diseases named in the same sentence as PVT1 in open-access papers (continued):
Sharing a sentence is not in itself a finding about the gene and the disease.
bladder cancer (continued). "Our data suggested PVT1 was an oncogene in bladder cancer and the tetracycline-inducible shRNA targeting PVT1 inhibited the expression of PVT1 in a dosage-dependent manner, and suppressed cell growth and induced apoptosis in bladder cancer cells." (PMID 26517688, 2015). "In this research, we found that the expression of non-coding RNA PVT1 was upregulated in bladder cancer tissues and cells." (PMID 26517688, 2015). "Cell growth arrest and increased apoptosis were observed in bladder cancer cells and these results indicated that PVT1 promoted the development of bladder cancer." (PMID 26517688, 2015). "The relative expression level of PVT1 was detected by performing real-time qPCR in a total of 32 patients with bladder cancer." (PMID 26517688, 2015). "Notably, suppression of PVT1 has decreased activity, proliferative potential, colony formation, migratory capacity, and invasiveness of bladder cancer cells." (PMID 36266723, 2022). "In conclusion, PVT1 plays an important role in bladder cancer and is a new biomolecular marker that may be used as a new therapeutic target and diagnostic tool." (PMID 36195846, 2022). "Moreover, lncRNA PVT1 promoted proliferation, migration and invasion of bladder cancer cells by increasing the expression of CDK1 which down-regulated miR-31." (PMID 35193513, 2022). "Taken together, PVT1-mediated reduction of miR-31 could increase expression of CDK1 in bladder cancer cells to enhance their proliferative potential, migration, and invasion." (PMID 36266723, 2022). "Moreover, CDK1 was recently identified as the target of a competing endogenous RNA (ceRNA) mechanism (lncRNA PVT1/miR-31) in the facilitation of bladder cancer progression." (PMID 34499615, 2021). "Interestingly, previous studies had also demonstrated PVT1 was dysregulated in prostate, kidney, and bladder cancer." (PMID 34335862, 2021). "As a microRNA sponge, PVT1 actively promotes the expression of b-cells lymphoma-2-associated transcription factor 1 (BCLAF1) to sponge miR-194-5p and subsequently increases malignant phenotypes of bladder cancer cells." (PMID 33188158, 2020). "Bioinformatics predicted potential sites to study the mechanism of PVT1 in bladder carcinomas." (PMID 33188158, 2020). "Nevertheless, the correlation with PVT1 and miR-194-5p was rarely studied in bladder carcinomas." (PMID 33188158, 2020). "Our studies displayed that PVT1 could sponge miR-194-5p to participate in the progression of the bladder carcinomas." (PMID 33188158, 2020). "Our study revealed that PVT1 sponging miR-194-5p could be the biomarker and therapeutic target for the diagnosis and treatment in the bladder carcinomas." (PMID 33188158, 2020). "Furthermore, PVT1 expression levels were significantly correlated with metastasis and advanced clinical stage in urinary system tumors, such as bladder cancer and renal carcinoma." (PMID 30083911, 2019). "Furthermore, SPRY4-IT1, MALAT1, linc-UBC1, lncRNA-LET, ZEB2-AS1, XIST, PVT1, and SNHG16 were significantly associated with lymph node metastasis status in patients with bladder cancer." (PMID 29899709, 2018). "This is the first report to illustrate the functions of PVT1 in bladder cancer." (PMID 26517688, 2015). "In conclusion, PVT1 promotes progression of bladder cancer cells." (PMID 26517688, 2015). "Here, we found that PVT1 was upregulated in bladder cancer tissues and cells." (PMID 26517688, 2015). "Furthermore we also used the emerging technology, synthetic biology, to create tetracycline-inducible small hairpin RNA (shRNA) vectors which silenced PVT1 in a dosage-dependent manner to inhibit the progression of bladder cancer." (PMID 26517688, 2015). "In conclusion, data suggest that PVT1 could be an oncogene and may be a therapeutic target in bladder cancer." (PMID 26517688, 2015). "CCK-8 assay was performed to observe whether si-PVT1 suppressed the proliferation of T24 and 5637 bladder cancer cells." (PMID 26517688, 2015).
bladder cancer (continued). "LncRNA PVT1 could enhance CDK1 expression via sponging miR-31 in bladder cancer." (PMID 32669972, 2020). "However, whether PVT1 also participates in development of bladder cancer is still unknown and needed to be studied." (PMID 26517688, 2015). "Several lncRNAs, including LINC00839, lncRNA PVT1, LUCAT1, LINC00958, and BCYRN1, exert a positive influence on both the proliferative viability and invasive capabilities of bladder cancer cells." (PMID 39628486, 2024). "Another study indicated that PVT1 promotes the expression of MDR1 and MRP1 in bladder cancer by activating the Wnt/β-catenin pathway, ultimately reducing the response of bladder cancer cells to doxorubicin and cisplatin." (PMID 36195846, 2022). "The PVT1/miR-194-5p/BCLAF1 axis was reportedly involved in the malignant progression and development of bladder cancer." (PMID 36195846, 2022). "Further experiments indicated that knockdown or overexpression of PVT1 restrained or promoted the malignant phenotype and WNT/β-catenin signaling in bladder cancer cells." (PMID 33188158, 2020). "Most importantly, PVT1 expression was closely related to histological grade and TNM stage in the bladder carcinomas." (PMID 33188158, 2020). "As a famous oncogene in other cancer, PVT1 is located in chromosome 8q24 and is closely near MYC which promotes progression of bladder cancer." (PMID 26517688, 2015). "However, the association between PVT1 and bladder cancer is not clear." (PMID 26517688, 2015). "For example, the expression of lncRNAs such as TUC338 and PVT1 can be used as biomarkers for early diagnosis of bladder cancer, while the expression of PCAT6, NRON, GAS6-AS2, SNHG3, lncRNA TP73-AS1, and LINC00641 can predict poor prognosis of bladder cancer." (PMID 37592177, 2023). "For example, it is reported that lncRNA PVT1, SUMO1P3 and CCAT2 can facilitate cell proliferation as well as repress cell apoptosis in bladder cancer." (PMID 33855047, 2021). "CCK8 asasy suggests that compared with the negative control, tetracycline-inducible PVT1 shRNA reduced cell proliferation significantly when added with 1 ug/ml doxycycline in bladder cancer T24 and 5637 cells (P < 0.001 in two cell lines)." (PMID 26517688, 2015). "PVT1 was also highly correlated with histological grade and TNM stage of bladder cancer." (PMID 26517688, 2015). "Bladder cancer T24 and 5637 cells were cultured in 6-well plates and transfected with plasmids (2 μg) expressing either the corresponding tetracycline-inducible PVT1 shRNA or the negative control." (PMID 26517688, 2015). "For bladder cancer, three lncRNAs have supporting evidence, and MEG3 and PVT1 have not been verified by the lncRNADisease database." (PMID 35186029, 2022).
plasmacytoma (28 papers, 2008 to 2025). Plasmacytoma is a localized mass of neoplastic monoclonal plasma cells that represents approximately 5% of all plasma cell neoplasms. "Long non-coding RNA plasmacytoma variant translocation (PVT1) binds to NRP1 and regulates its expression but knock down of PVT1 suppresses the growth and metastasis of Circulating Endothelial cells (CEC), explaining the role of NRP1." (PMID 40277760, 2025). "The PVT1 symbol was first used for the mouse ortholog (Pvt1) following its discovery as the major locus for murine plasmacytoma variant translocations." (PMID 35880706, 2023). "The long non-coding RNA (lncRNA) PVT1 was first found to activate variant translocations in the plasmacytoma of mice." (PMID 35965522, 2022). "Plasmacytoma Variant Translocation 1 (PVT1) is a lncRNA longer than 500 nucleotides, first found in mouse plasmacytoma and then reported to be involved in the oncogenesis of many types of cancers." (PMID 32992461, 2020). "Our previous study also validates PVT1 (in humans, PVT1, for plasmacytoma variant translocation) as a critical regulator of gemcitabine chemosensitivity in PC cells using a genome‐wide and piggyBac transposon‐based genetic screening platform." (PMID 30341811, 2018). "First, all of the 10 CTXs occurring around S or C regions of the Igh locus were translocated to the c-myc or plasmacytoma variant translocation 1 (Pvt1) locus on chromosome 15 (8 vs 2, respectively)." (PMID 26740101, 2016). "The Pvt1 locus contains a long non-coding RNA gene, which is a frequent translocation partner in mouse plasmacytomas and variants of human Burkitt’s lymphomas (BL)." (PMID 26740101, 2016). "The human PVT1 gene (also known as Pvt1 oncogene) is a long intergenic noncoding RNA (lincRNA) homologous to the mouse plasmacytoma variant translocation gene (Pvt1)." (PMID 25883951, 2015). "One locus at 8q24.21 comprised the representative oncogenes of myelocytomatosis (MYC) and plasmacytoma variant translocation 1 (PVT1) (4.5%)." (PMID 24944681, 2014). "Ever since its discovery in 1984, the Pvt1 locus (in humans PVT1, for plasmacytoma variant translocation) has remained enigmatic." (PMID 18194563, 2008). "A common manifestation of plasmacytoma variant translocation 1 (PVT1) locus amplification is the formation of DMs, which then participate in DM amplification or form new fusion genes, resulting in high PVT1 expression in tumors and tumorigenicity." (PMID 35494014, 2022). "The mouse plasmacytoma variant translocation (Pvt1) gene has been identified as a candidate oncogene located at chromosome 15 and encodes a lincRNA homologous to that encoded by the human PVT1 gene, which maps to chromosome 8." (PMID 30925926, 2019). "The human PVT1 lncRNA is located on chromosome 8 telomeric to the c-Myc gene and is frequently involved in the translocations occurring in variant Burkitt’s lymphomas and murine plasmacytoma; PVT1 presents two MYC-binding sites in its promoter, which are bound and transactived by c-MYC." (PMID 29739426, 2018). "At first, lncRNA PVT1 was discovered as an activator of MYC in mouse plasmacytoma translocation, and later it was found that lncRNA PVT1 played a carcinogenic part in various human cancers." (PMID 35399100, 2022). "The plasmacytoma variant translocation 1 (PVT1) is an oncogenic lncRNA, located at the 8q24 region, was discovered in murine plasmacytoma in 1985." (PMID 34922601, 2021). "PVT1 is homologous evolutionary conserved lncRNA first identified in murine plasmacytomas, while in humans it resides in 8q24 region near to the c-Myc locus." (PMID 32106407, 2020). "LncRNA PVT1, an activator of MYC, was first identified in plasmacytoma variant translocations in mice in 198431." (PMID 33067424, 2020). "The plasmacytoma variant translocation 1 (PVT1) gene encodes a lncRNA and was first discovered as an activator of MYC in murine plasmacytoma variant translocation in 1984." (PMID 31309249, 2019).
plasmacytoma (continued). "Plasmacytoma variant translocation 1 (PVT1) is a lncRNA gene, which was first discovered in mouse plasmacytoma in the mid 1980s, and in recent years, many studies have found that PVT1 is involved in the occurrence and development of various malignant tumors." (PMID 29445147, 2018). "The functional significance of the Pvt1 locus in the oncogenesis of Burkitt's lymphoma and plasmacytomas has remained a puzzle." (PMID 18194563, 2008). "Recently, the significance of plasmacytoma PVT1 expression in OS patients was determined." (PMID 32021563, 2020). "In these plasmacytomas, the expression of the (truncated) Pvt1 transcripts is increased." (PMID 18194563, 2008).
nasopharyngeal carcinoma (27 papers, 2018 to 2025). A carcinoma arising from the nasopharyngeal epithelium. "For example, LncRNA PVT1 enhances the sphere-forming ability of nasopharyngeal cancer CSCs, and LncRNA HOTTIP promotes tumorigenicity and spheroid formation in pancreatic CSCs, as shown by both in vitro and in vivo experiments." (PMID 41008534, 2025). "The lncRNA PVT1, for example, modulates nasopharyngeal carcinoma cell proliferation by stabilizing HIF-1α and activating KAT2A acetyltransferase." (PMID 37946265, 2023). "In nasopharyngeal carcinoma (NPC), lncRNA PVT1 has been associated with unfavorable prognosis and radioresistance promotion." (PMID 36294743, 2022). "In nasopharyngeal cancer, lncRNA PVT1 can act as a scaffold for the chromatin modifier KAT2A, recruiting the nuclear receptor-binding protein TIF1β to activate NF90 transcription, thereby increasing HIF-1α and upregulating radioresistance." (PMID 35600868, 2022). "PVT1 silencing triggers apoptosis and suppresses the radioresistance of nasopharyngeal cancer cells by inhibiting DNA repair." (PMID 36230902, 2022). "The lncRNA PVT1, defined as a factor indicating poor prognosis, enhances radioresistance by regulating apoptosis in nasopharyngeal carcinoma." (PMID 34863180, 2021). "PVT1 fostered radiotherapy resistance in nasopharyngeal carcinoma by downregulating cleaved caspase-9, cleaved caspase-7, and cleaved PARP, thereby inhibiting apoptosis and subsequently causing radiation resistance." (PMID 32117705, 2020). "LncRNA PVT1 improves DNA repair and suppresses cell apoptosis of nasopharyngeal cancer cells." (PMID 36230902, 2022). "LncRNA PVT1 regulates DNA repair in nasopharyngeal carcinoma." (PMID 35173610, 2021). "Specifically, PVT1 can promote the radiotherapy resistance of nasopharyngeal carcinoma." (PMID 29445147, 2018). "For instance, the oncogenic lncRNA PVT-1 is upregulated in nasopharyngeal carcinoma (NPC), which plays an important role in the radiation resistance of NPC by activating the KAT2A acetyltransferase and stabilizing HIF-1α." (PMID 39937018, 2025). "In nasopharyngeal carcinoma, hsa-miR-1207 has been shown to be inhibited by non-coding RNA Pvt1 or long non-coding RNA 319, which may act as a sponge to miRNAs, inducing cellular proliferation via PI3K/AKT, or carcinogenesis via KLF12 signaling pathways, respectively." (PMID 38146340, 2023). "Recent research has revealed that PVT1 is up regulated in nasopharyngeal carcinoma tissues and its overexpression predicts a poor prognosis for NPC patients." (PMID 34922601, 2021). "In nasopharyngeal carcinoma cells (NPC), both lncRNA PVT1 and lncRNA DANCR can interact with HIF-1α to influence NPC progression." (PMID 33109235, 2020). "However, the role and mechanism of action of PVT1 in the carcinogenesis and progression of nasopharyngeal carcinomas (NPCs) remains unclear." (PMID 29445147, 2018). "PVT1 was upregulated in patients with nasopharyngeal carcinoma (NPC)." (PMID 32585857, 2020). "Of note, the observation of HIF-1α protein reduction corroborated the hypothesis of a deregulation of hypoxia signaling by PVT1, which has been already demonstrated to have a key role in HIF-1α stabilization in nasopharyngeal carcinoma." (PMID 39922814, 2025).
diabetic nephropathy (25 papers, 2011 to 2025). "PVT1, located in a diabetic nephropathy susceptibility locus, drives mesangial expansion and enhances TGF-β signaling, representing another therapeutic target in CKD." (PMID 41300780, 2025). "Genetic evidence supports this link: PVT1 was identified as a candidate gene for end-stage renal disease in type 2 diabetes and PVT1 variants (e.g., rs3931283) associated with diabetic kidney disease and renal function markers in patients with type 2 diabetes." (PMID 41303683, 2025). "LncRNA plasmacytoma variant translocation 1 (PVT1), located on chromosome 8q24.21, has been found to be associated with diabetic kidney disease." (PMID 39349450, 2024). "Plasmacytoma variant translocation 1 (PVT1) is the first lncRNA to be associated with end-stage renal disease in Type 1 and 2 diabetes, and its function has been characterized in diabetic kidney disease." (PMID 32295041, 2020). "The plasmacytoma variant translocation gene PVT1 had been linked to diabetic nephropathy by the finding that variants in this gene are associated with the development of end-stage renal disease (ESRD) in both type 1 and 2 diabetes mellitus." (PMID 31277300, 2019). "We have previously shown that variants in PVT1 are associated with diabetic kidney disease, and that its expression is strongly regulated by glucose." (PMID 24204837, 2013). "Delineation of the relationship between TGFB1 and PVT1 therefore represents a critical component toward understanding the molecular mechanisms underlying the regulation of ECM in diabetic nephropathy." (PMID 21526116, 2011). "Furthermore, knockdown of Pvt1 has been implicated in diabetic nephropathy as a mediator of podocyte apoptosis." (PMID 33804736, 2021). "Our group identified plasmacytoma variant translocation 1 (PVT1) as a potential locus for diabetic end-stage renal disease using a genome-wide association approach in Native Americans, and PVT1 variants have since been associated with diabetic kidney disease in other populations." (PMID 28829354, 2017). "We show that PVT1 is regulated by hyperglycemia, and may mediate susceptibility to diabetic kidney disease through effects involving ECM accumulation." (PMID 21526116, 2011). "PVT1 is significantly upregulated in conditions such as diabetic nephropathy, arthritis, cardiomyopathy, cataracts, and non-alcoholic fatty liver disease." (PMID 39498440, 2024). "Silencing PVT1 increases expressions of Bax and cleaved caspase-3 and thus inhibits apoptosis in diabetic nephropathy." (PMID 34775377, 2021). "They recently reported that miR-1207-5p, a PVT1-derived microRNA, was also independently involved in pathogenesis of diabetic nephropathy." (PMID 29085333, 2017). "Here, we provide additional biological evidence supporting a role for PVT1 in the pathogenesis of diabetic nephropathy." (PMID 21526116, 2011). "We chose to initiate the functional characterization of PVT1 in this cell type because one of the key hallmarks of diabetic nephropathy is expansion of mesangium." (PMID 21526116, 2011). "PVT1 (plasmacytoma variant translocation 1) is the first lncRNA identified to be associated with diabetic nephropathy, where single-nucleotide polymorphisms (SNPs) significantly associated with end-stage renal disease (ESRD) of type 2 diabetes were located in PVT1." (PMID 35736633, 2022). "Based on these findings, we hypothesized that PVT1 may contribute to the increased accumulation of ECM in the glomeruli characteristic of diabetic nephropathy." (PMID 24204837, 2013). "The goal of this study, therefore, was to identify possible molecular mechanisms by which PVT1 may contribute to the development and progression of diabetic nephropathy in mesangial cells." (PMID 21526116, 2011). "The goal of this study was to identify possible molecular mechanisms by which PVT1 may contribute to the development and progression of diabetic kidney disease." (PMID 21526116, 2011).
diabetic nephropathy (continued). "Further characterization of miR-1207-5p and its host gene, the long non-coding RNA PVT1, may yield new insights into the complex pathogenesis of diabetic nephropathy, and may contribute to the development of new and more effective treatments based on these new potential therapeutic targets." (PMID 24204837, 2013). "PVT1 also regulates the expression of ECM-related proteins, and combined, these results suggest a role for this gene in the development of diabetic nephropathy." (PMID 24204837, 2013). "Further study reveals that high glucose levels induced PVT1 to stimulate TGF-β1, PAI-1, and FN1 expression, which is further amplified by PVT1-derived miR-1207-5p to accelerate ECM accumulation in the diseased glomeruli of diabetic nephropathy (DN)." (PMID 35736633, 2022). "Reduction of PVT1 expression by siRNA significantly affected mRNA and protein levels of all ECM components examined, suggesting that PVT1 contributes to ECM deposition in the glomeruli, one of the major pathological features of diabetic nephropathy." (PMID 21526116, 2011). "Similarly, PVT1 and PRINS contribute to podocyte injury via TGF-β1/FN1 accumulation and Smad7-dependent pathways, respectively; conversely, decreased LINC01619 correlates with worse diabetic nephropathy, acting through miR-27a and ER stress." (PMID 41300780, 2025).